UBR3 (ubiquitin protein ligase E3 component n-recognin 3)
Description:
E3 ubiquitin-protein ligase which is a component of the N-end rule pathway (By similarity). Does not bind to proteins bearing specific N-terminal residues that are destabilizing according to the N-end rule, leading to their ubiquitination and subsequent degradation (By similarity). May play a role in Shh signaling by mediating the ubiquitination of Kif7 (By similarity). May be important for MYH9 function in certain tissues, possibly by regulating the ubiquitination of MYH9 and consequently affecting its interaction with MYO7A.
Synonyms: KIAA2024; ZNF650; DKFZp434P117; FLJ37422
Tractability: Antibody: UniProt predicts a signal peptide or a membrane-spanning region. PROTAC: ubiquitination databases record sites on it; its protein half-life has been measured.
Gene: Protein-coding gene on chromosome 2 (169,827,442 to 170,084,131, forward strand). Ensembl gene ENSG00000144357.
Subcellular location: Membrane
Subcellular location (Human Protein Atlas): Nucleoli; Nucleoplasm
Gene Ontology:
Molecular function: protein binding; ubiquitin protein ligase activity; ubiquitin-protein transferase activity; zinc ion binding
Biological process: embryo development ending in birth or egg hatching; protein ubiquitination; sensory perception of smell; suckling behavior; ubiquitin-dependent protein catabolic process; ubiquitin-dependent protein catabolic process via the N-end rule pathway; negative regulation of calcium ion transmembrane transport via high voltage-gated calcium channel; positive regulation of protein catabolic process; proteasome-mediated ubiquitin-dependent protein catabolic process
Cellular component: cytoplasm; ubiquitin ligase complex; membrane
Genetic constraint (gnomAD): Loss-of-function variants: 64 observed, 184.36 expected, observed/expected ratio (o/e) 0.35, 90% interval 0.28 to 0.43. The upper end of that interval is the gene's LOEUF score, 0.43, which puts it in group 1 of 6, group 1 being the genes least tolerant of losing a copy. Missense variants: 1,372 observed, 1,854.6 expected, observed/expected ratio (o/e) 0.74, 90% interval 0.71 to 0.77. Synonymous variants: 617 observed, 639.31 expected, observed/expected ratio (o/e) 0.97, 90% interval 0.9 to 1.03.
Homologues: Orthologues: chimpanzee UBR3 (99% identical), macaque UBR3 (99% identical), dog UBR3 (97% identical), pig UBR3 (97% identical), rabbit UBR3 (97% identical), mouse Ubr3 (95% identical), rat Ubr3 (95% identical), guinea pig UBR3 (87% identical), tropical clawed frog ubr3 (80% identical), zebrafish ubr3 (73% identical), Drosophila melanogaster Ubr3 (36% identical), Caenorhabditis elegans F10G7.10 (19% identical). Paralogues in human: UBR2 (20% identical), UBR1 (20% identical).
Diseases named in the same sentence as UBR3 in open-access papers:
UBR3 is named in the same sentence as 22 diseases in open-access papers, as found by Europe PMC text mining. Sharing a sentence is not in itself a finding about the gene and the disease. The quoted sentences say what the papers report.
developmental delay (2 papers, 2020 to 2024). "The most significant finding in Th cells was linked to UBR3 (P = 3.47 × 10–11, q = 0.0008), which has been suggested as a candidate gene for developmental delay in children." (PMID 38778395, 2024). "In particular, our results suggest novel candidate genes for retinal degeneration with anophthalmia (EPHA6), developmental delay with speech impairment (KLF13), and developmental delay with brain dysembryoplastic neuroepithelial tumor (UBR3)." (PMID 32344861, 2020). "The most interesting genes that were damaged by the BCTs are: EPHA6 (the first case with an optic phenotype in humans), UBR3 (the second case with developmental delay in humans), KLF13 (second case with developmental delay in humans)." (PMID 32344861, 2020). "Additionally, one male patient with a heterozygous stop codon in UBR3 and developmental delay (phenotype not precisely described) has been reported." (PMID 32344861, 2020).
aneurysm (1 paper, 2021). Bulging or ballooning in an area of an artery secondary to arterial wall weakening. "Through literature searches we found that the participant of ubiquitination related proteins (e.g. UCHL1, RNF213, UBR3, ARIH1) in pathogenesis of above-mentioned human aneurysm subtypes (ASH, AAA, CA, AA, AD) has been widely reported before." (PMID 34895131, 2021).
Arrhythmia (1 paper, 2015). Any cardiac rhythm other than the normal sinus rhythm. "This discovery has certain pathophysiological implications, suggesting a potential association of UBR3/6 with heart diseases such as arrhythmias." (PMID 26059563, 2015).
cardiac arrhythmia (1 paper, 2015). Any disturbances of the normal rhythmic beating of the heart or MYOCARDIAL CONTRACTION. "It is likely that UBR3/6 have the potential to be a therapeutic target for cardiac arrhythmias." (PMID 26059563, 2015).
congenital heart disease (1 paper, 2020). A heart disease that is present at birth. "On the other hand, UBR3 (LOEUF = 0.357, DOMINO = 0.7) is an interesting candidate as it encodes an ubiquitin ligase whose defects, based on six described variants, have been linked to ASD or congenital heart disease." (PMID 32344861, 2020).
cyclopia (1 paper, 2016). "Similarly, loss of ubr3 does not result in cyclopia or inner ear defects, showing that these mutants have a less severe phenotype when compared to smoothened mutant animals." (PMID 27195754, 2016).
esophageal carcinoma (1 paper, 2023). A primary or metastatic malignant neoplasm involving the esophagus. "On the contrary, the differentiated expression of UBR3 were illustrated to be downregulated in a series of cancers, while merely upregulated in esophageal carcinoma (ESCA) and stomach adenocarcinoma (STAD)." (PMID 37854190, 2023).
hearing loss (1 paper, 2016). "Ubr3 negatively regulates the mono-ubiquitination of non-muscle Myosin II, a protein associated with hearing loss in humans." (PMID 27331610, 2016).
intervertebral disc degeneration (1 paper, 2024). "UBR3 plays a stimulative role in intervertebral disc degeneration trough increase inflammation." (PMID 38370381, 2024).
intracranial aneurysm (1 paper, 2024). "It was reported that the polymorphisms of UBR3 and MYO3B were related to saccular intracranial aneurysm in Portugal39." (PMID 38370381, 2024).
ischemic stroke (1 paper, 2015). A stroke disorder caused by obstruction of blood flow to the brain, due to thrombotic (local blood clot formation) or embolic (due to a blood clot or other material traveling from another site) event. "UBR3 (formerly referred to as ZNF650) has been associated to neurological phenotypes, namely ischemic stroke and temporal brain volume, and therefore its role in IA warrants further investigation." (PMID 26186006, 2015).
lupus nephritis (1 paper, 2023). Glomerulonephritis in the context of systemic lupus erythematosus. "The UBR3 mRNA levels in patients with lupus nephritis correlated with SLEDAI-2K and the index of histological activity." (PMID 37958966, 2023).
ovarian carcinoma (1 paper, 2024). A malignant neoplasm originating from the surface ovarian epithelium. "Interestingly, the E3 ligase UBR3, which is amplified and overexpressed in ovarian cancer, was found to play a nonredundant role in promoting ovarian cancer growth and metastasis." (PMID 39402303, 2024).
uremia (1 paper, 2013). A clinical syndrome associated with the retention of renal waste products or uremic toxins in the blood. "However, probe sets of the protein-degradation machinery, e.g. UBE2E1, USP32, UBE2Q2, and UBR3 were inhibited in uremia, indicating that evaluation of the ubiquitin-proteosome machinery requires more detailed investigation." (PMID 23809614, 2013).
Usher syndrome (1 paper, 2016). A syndromic diseae characterized by the association of sensorineural deafness (usually congenital) with retinitis pigmentosa and progressive vision loss. "We show that ubr3 mutants phenocopy pathogenic variants of Myosin II and that Ubr3 interacts genetically and physically with three Usher syndrome proteins." (PMID 27331610, 2016). "We show that ubr3 mutations are phenotypically similar to known pathogenic variants of Myosin II and that Ubr3 physically and genetically interacts with Drosophila homologues of the Usher syndrome proteins Protocadherin 15 (Pcdh15) and Sans." (PMID 27331610, 2016). "The precise mechanical function performed by these two myosins in the scolopale cells of Johnston’s organ involves other homologues of Usher syndrome type I genes given that the morphological phenotype of ubr3 mutants is enhanced by loss of either Sans or Cad99C (A’’)." (PMID 27331610, 2016). "We also tested whether a second Usher syndrome homologue, Sans, interacts with Ubr3 and Cul1." (PMID 27331610, 2016).
cancer (3 papers, 2021 to 2025). A tumor composed of atypical neoplastic, often pleomorphic cells that invade other tissues. "By contrast, the percentage of cancer samples with UBR3 mutation was relative less, with mutation rate at 9.98% in UCEC being the top one among all the cancers." (PMID 37854190, 2023). "UBR3 transcripts were more abundant in cancer cell lines than in normal tissues." (PMID 33836029, 2021). "Transcript expression patterns for SHANK1, UBR3, and BSN in cancer cell lines and Clontech’s normal human tissue panels were analysed using qPCR, detection of the exon encoding the cross-reactive peptide." (PMID 33836029, 2021).
tumor (2 papers, 2023 to 2024). "To date, there is a dearth of literature exploring the association between UBR3 and tumor diseases." (PMID 38370381, 2024). "Despite of the predicted role of being the tumor driver gene, the mutation of UBR3 might not contribute dominantly to the pathogenesis of THPT." (PMID 37854190, 2023).
UBR3 also shares sentences with these, for which no sentence is quoted: glioma (1 paper); heart diseases (1); Intellectual disability (1); laryngeal carcinoma (1); oral cancers (1).